TFEB (transcription factor EB)
Diseases named in the same sentence as TFEB in open-access papers (continued):
Sharing a sentence is not in itself a finding about the gene and the disease.
periodontitis (4 papers, 2020 to 2025). An acute or chronic inflammatory process that affects the tissues that surround and support the teeth. "The results of IHC showed that, compared with the control group, the expression of TFEB increased significantly in the periodontitis (Pg + GFP) and arthritis (CIA + GFP) groups, and the expression of TFEB was highest in the comorbidity group (CIA + Pg + GFP)." (PMID 31737959, 2020). "The infiltration of macrophages, TLR9, autophagy proteins (TFEB and LC3) and inflammatory cytokines increased in the periodontitis‐with‐RA group and was reduced by the inhibition of Ctsk in the periodontal region." (PMID 31737959, 2020). "Our in vivo experiment found that RA can increase the expression of autophagy proteins TFEB and LC3A/B in the periodontitis lesion area, upregulate the secretion of inflammatory factors Tnfα and Il6, promote the infiltration of macrophages and finally aggravate bone destruction." (PMID 31737959, 2020).
Renal cyst (4 papers, 2021 to 2023). A fluid filled sac in the kidney. "TFEB is the key transcriptional regulator of genes that harbors the CLEAR motif, and TFEB has been implicated in cystic kidney disease." (PMID 37256068, 2023). "CTSD expression was also significantly upregulated in renal cysts compared with normal human renal tubules and correlated with renal cystic epithelial cell nuclear TFEB staining." (PMID 36794754, 2023). "GPNMB staining was significantly higher in renal cysts that were TFEB positive compared with normal human renal tubules." (PMID 36794754, 2023). "Renal cysts exhibited strong staining of TFEB with evidence of nuclear translocation, which colocalized with the nuclear marker Hoechst 33342." (PMID 36794754, 2023). "The role of TFEB, a transcriptional regulator of lysosomal function, was explored in several models of renal cystic disease and human ADPKD tissue sections." (PMID 36794754, 2023). "Nuclear TFEB translocation was uniformly observed in cystic epithelia in each model of renal cystic disease examined." (PMID 36794754, 2023). "Noncanonical activation of TFEB is characteristic of cystic epithelia in multiple models of renal cystic disease including those associated with loss of Pkd1." (PMID 36794754, 2023). "Using several models of renal cystic disease, including those associated with loss of folliculin and polycystin-1 (PKD1) activities, it was observed that nuclear TFEB translocation and functional responses associated with TFEB activation characterize cyst-lining epithelia." (PMID 36794754, 2023). "Nuclear TFEB translocation is an underappreciated signaling pathway for cystogenesis that may represent a new paradigm for cystic kidney disease." (PMID 36794754, 2023).
Salmonella Infections (4 papers, 2021 to 2024). Infections with bacteria of the genus SALMONELLA. "Collectively, these results suggest that both LPS and Salmonella infections enhance the transcriptional activity of TFEB in the colonic epithelium." (PMID 38711975, 2024). "Given these discrepancies, we sought to better understand the relationship between Salmonella infection and TFEB activation." (PMID 38051049, 2024). "To further demonstrate this upregulation of LAMP1 and LC3 by LPS and Salmonella infection, we used shRNA to silence the expression of TFEB in the Caco 2 cells and then treated these engineered cells with LPS or Salmonella infection." (PMID 38711975, 2024). "In line with the histochemical analysis, Salmonella infection enhanced the nuclear translocation of TFEB." (PMID 38711975, 2024). "Furthermore, TFEB was translocated to the nucleus in colonic enterocytes after Salmonella infection in C57/B6 mice." (PMID 38711975, 2024). "Hence, these findings indicate that the Salmonella infection results in the activation of TFEB in colonic epithelial cells in vivo." (PMID 38711975, 2024). "Overall, we reveal a complex interplay between TFEB and Salmonella infection conditions." (PMID 38051049, 2024). "Interestingly, the small molecule autophagy inducer acacetin can reduce intracellular Salmonella infection by inducing TFEB dephosphorylation, thereby increasing autolysosomal and lysosomal populations in the cells and restricting replication of intracellular Salmonella." (PMID 37771590, 2023).
triple-negative breast carcinoma (4 papers, 2024 to 2025). An invasive breast carcinoma which is negative for expression of estrogen receptor (ER), progesterone receptor (PR), and human epidermal growth factor receptor 2 (HER2). "In triple-negative breast cancer (TNBC), neddylated TRIM25 facilitates K63-linked ubiquitination and nuclear translocation of TFEB (transcription factor EB), activating autophagy-related genes and inducing PTX resistance." (PMID 41315221, 2025). "In contrast, in triple-negative breast cancer (TNBC), upregulated circEGFR binding to ANXA2 promotes ANXA2 translocation to the plasma membrane, leading to the release of TFEB from the ANXA2-TFEB complex and causing TFEB nuclear translocation." (PMID 40234383, 2025).
acute pancreatitis (3 papers, 2022 to 2024). An acute inflammatory process that leads to necrosis of the pancreatic parenchyma. "Activation of α7 nicotinic acetylcholine receptor (α7nAChR), integral to the cholinergic anti-inflammatory pathway, protects against acute pancreatitis by enhancing transcription factor EB (TFEB)-regulated autophagy." (PMID 39403146, 2024). "The deletion of transcription factor EB (TFEB) is another mechanism to reduce autophagy in acute pancreatitis." (PMID 37519748, 2023). "Depletion of TFEB (transcription factor of EB) is another mechanism responsible for reduced autophagy in the acute pancreatitis." (PMID 36010591, 2022). "Genetic ablation of this transcription factor increased the severity of experimental acute pancreatitis, whilst TFEB overexpression was protective." (PMID 36010591, 2022). "TFEB is rapidly degraded in the caerulein model of acute pancreatitis resulting in an insufficient autophagy." (PMID 36010591, 2022).
angiomyolipoma (3 papers, 2021 to 2025). A neoplasm with perivascular epithelioid cell differentiation often associated with tuberous sclerosis. "Indeed, MITF is considered a hallmark gene of lymphangioleiomyomatosis (LAM) and angiomyolipomas in TSC44,45, based on upregulation of genes that are known transcriptional targets of MITF/TFE3/TFEB/TFEC including MelanA and Cathepsin K46,47." (PMID 38195686, 2024). "Typically, MelanA is expressed in angiomyolipoma (AML), TFE3-rearranged RCC (TFE3-RCC), and TFEB-altered RCC (TFEB-RCC)." (PMID 40584698, 2025). "Other tumor types included papillary RCC (n = 10), angiomyolipoma (n = 6), oncocytoma (n = 6), chromophobe RCC (n = 3), unclassified RCC (n = 3), hybrid oncocytic tumors (n = 2), and TFEB-amplified RCC (n = 1) (eFigure in the Supplement)." (PMID 34767027, 2021).
cognitive decline (3 papers, 2021 to 2025). "The purpose of this study is to explore whether chronic alcohol consumption worsens the age-related decline in TFEB-mediated lysosomal biogenesis in the brain and exacerbates cognitive decline associated with aging." (PMID 39766244, 2024). "To investigate whether changes in mitophagy reflect cognitive decline in FTLD individuals, we correlated the levels of mitophagy biomarkers (PINK1, ULK1, BNIP3L, TFEB) with global cognition (MMSE) and cognitive composite scores." (PMID 39972393, 2025).
fibrosis (3 papers, 2020 to 2022). the formation of excess fibrous connective tissue in an organ or tissue in a reparative or reactive process. "Here, we show that Albumin-CRE-driven TFEB overexpression in the liver of transgenic mice results in a severe phenotype characterized by a progressive increase in liver mass, hyperplasia of bile ducts, altered biliary tree structure, multifocal biliary cystic hyperplasia, and fibrosis." (PMID 32424153, 2020).
Hypercholesterolemia (3 papers, 2020 to 2024). An increased concentration of cholesterol in the blood. "We found that hepatic TFEB overexpression significantly reduced WD-induced hepatic and gallbladder cholesterol accumulation and hypercholesterolemia, which correlated with significantly increased bile acid pool." (PMID 32681035, 2020). "In this study, we show that hepatic TFEB deficiency reduces hepatic CYP7A1 expression and sensitizes mice to hypercholesterolemia upon WD challenge." (PMID 32681035, 2020). "Finally, hepatic TFEB overexpression by adenovirus significantly reduces hepatic and plasma levels of cholesterol, while hepatic TFEB knockdown exacerbates hypercholesterolemia in Western diet-fed mice." (PMID 35625599, 2022). "We show that TFEB induces cholesterol 7α-hydroxylase (CYP7A1) in human hepatocytes and mouse livers and prevents hepatic cholesterol accumulation and hypercholesterolemia in Western diet-fed mice." (PMID 32681035, 2020).
kidney damage (3 papers, 2022 to 2025). "The upregulation of TFEB by Klotho could explain some of the described beneficial effects of this protein in the FK506-induced nephropathy models." (PMID 36829798, 2023). "FK506 significantly reduces the protein levels of TFEB in nephropathy mice model and in HK-2 cells." (PMID 36829798, 2023).
lipid metabolism disorders (3 papers, 2022 to 2024). "In an obese mouse model, TFEB-knockout resulted in lipid metabolism disorders and metabolic pathway imbalances." (PMID 36552704, 2022).
lymphangioleiomyomatosis (3 papers, 2021 to 2024). A multifocal neoplasm with perivascular epithelioid cell differentiation affecting almost exclusively females of child-bearing age. "In contrast, a recent publication reported that renal tumors, lymphangioleiomyomatosis, and kidneys from TSC2 heterozygous mice display increased lysosomal biogenesis that occurs due to hypo-phosphorylation and nuclear translocation of TFEB." (PMID 34685691, 2021). "We found that TFEB is predominantly nuclear in Human Melanoma Black-45 (HMB45) and NPC1-positive lymphangioleiomyomatosis (LAM) nodules, the pulmonary manifestation of TSC37." (PMID 34253722, 2021).
metastatic disease (3 papers, 2019 to 2024). "In terms of overall expression level, MITF had a 4- and 15-fold higher mRNA expression than that of TFEB and TFE3, respectively, in the metastatic tumors (Sup." (PMID 30705290, 2019).
Niemann-Pick type C disease (3 papers, 2022 to 2025). "In support of our findings, a handful of studies also described enhanced TFEB transcriptional activity by Abl inhibition in other neurometabolic disorders such as ALS or Niemann-Pick type C disease." (PMID 37838776, 2023). "A recent publication suggested that TFEB de-phosphorylation and nuclear translocation in a model of Niemann-Pick type C disease (NPC) upon c-Abl inhibition with dasatinib." (PMID 35392170, 2022).
osteoporosis (3 papers, 2024 to 2025). A condition of reduced bone mass, with decreased cortical thickness and a decrease in the number and size of the trabeculae of cancellous bone (but normal chemical composition), resulting in increased fracture incidence. "Overall, these results demonstrate TFEB-driven stimulation of autophagy in osteoblast lineage cells is associated with increased bone formation and strength and may represent an effective approach to combat osteoporosis." (PMID 40728889, 2025). "However, little is known about the relationship between TFEB activities and osteoporosis." (PMID 39164234, 2024).
papillary carcinoma (3 papers, 2016 to 2023). A malignant epithelial neoplasm characterized by a papillary growth pattern. "Here, we show that kidney-specific TFEB overexpression in transgenic mice, resulted in renal clear cells, multi-layered basement membranes, severe cystic pathology, and ultimately papillary carcinomas with hepatic metastases." (PMID 27668431, 2016). "However, kidney-specific TFEB overexpression in transgenic mice results in papillary carcinomas with severe cystic pathology via the WNT pathway." (PMID 36649084, 2023).
silicosis (3 papers, 2020 to 2025). Silicosis is a respiratory disease caused by breathing in (inhaling) silica dust. "Knockout of TFEB aggravates silica-induced AM apoptosis by disruption of the autophagy-lysosomal system in the silicosis mice model." (PMID 33466366, 2021). "Future experiments should focus on the role of selective autophagy and the relationship between mitophagy, lysophagy, and reticulophagy in Tre-treated silicosis or TFEB-overexpressing or silenced mouse models." (PMID 31947943, 2020). "Furthermore, in a model of silicosis, trehalose alleviated lysosomal dysfunction and reduced tissue structural damage by activating the TFEB-mediated autophagy-lysosome system." (PMID 40584613, 2025). "Our study suggests that restoration of autophagy-lysosomal function by Tre-induced TFEB activation may be a novel strategy for the treatment of silicosis." (PMID 31947943, 2020). "The nuclear translocation of TFEB in the AMs of mice with silicosis could serve a protective role against CS-induced lysosomal disruption." (PMID 31947943, 2020). "In conclusion, these results uncover a protective role of TFEB-mediated autophagy in silicosis." (PMID 31947943, 2020). "However, the nuclear transfer of TFEB activated by Tre relieves silica-induced lysosome damage and disorder of autophagic substrates degradation, reducing apoptosis in the mice-derived AM or AM of silicosis patients." (PMID 33466366, 2021). "Therefore, in this study, we assessed the role of TFEB in silicosis models and investigated whether Tre could alleviate CS-induced inflammation and fibrosis via the activation of the TFEB-mediated autophagy-lysosomal system." (PMID 31947943, 2020).
tuberous sclerosis complex (3 papers, 2023 to 2024). "There is precedent, however, for simultaneous activation of TFEB/TFE3 and mTORC1 pathways in disease conditions, as we previously reported for the first time in tuberous sclerosis complex." (PMID 38386415, 2024). "Moreover, in the renal tumours from mouse models of tuberous sclerosis complex (TSC), the absence of Tsc2 inhibits FLCN and thus promotes RagC/DGTP formation, establishing a non‐canonical means of preventing mTORC1‐mediated phosphorylation of TFEB, thereby driving its nuclear translocation." (PMID 37728021, 2023).
alveolar soft part sarcoma (2 papers, 2021 to 2022). An alveolar soft part sarcoma occurring in adults. "Translocations and rearrangements of TFE3 and TFEB are associated with a rare subtype of kidney cancer termed translocation-renal cell carcinoma (tRCC) and alveolar soft part sarcomas (ASPS), a rare lung cancer variant." (PMID 35665902, 2022).
aneurysm (2 papers, 2022 to 2025). Bulging or ballooning in an area of an artery secondary to arterial wall weakening. "Dysregulated TFEB has been detected in patients with aneurysms, which is highly associated with smooth muscle cell apoptosis and macrophage inflammation, but the underlying molecular mechanisms are still missing 49,50." (PMID 40963913, 2025).
Arrhythmia (2 papers, 2021 to 2025). Any cardiac rhythm other than the normal sinus rhythm. "In addition, it is also of interest that the pharmaceutical compound amiodarone, used to treat arrhythmias, induces autophagy by the transcription factor EB (TFEB), which leads to clearance of M. marinum and M. avium by autophagic mechanisms mediated by macrophages." (PMID 40430792, 2025).
autoimmune disease (2 papers, 2024 to 2025). A disorder resulting from loss of function or tissue destruction of an organ or multiple organs, arising from humoral or cellular immune responses of the individual to their own tissue constituents. "Persistent TFEB activation could overdrive autophagy, potentially causing damage to healthy proteins and organelles, and this can also impair immune function, increasing the risk of autoimmune diseases." (PMID 39897039, 2025). "Furthermore, in a mouse model of autoimmune disease, deletion of TFEB in Treg cells resulted in reduced Treg accumulation and impaired Treg function." (PMID 38664707, 2024).
Birt-Hogg-Dube syndrome (2 papers, 2021 to 2022). "Of note, FLCN is mutated in Birt-Hogg-Dubé syndrome patients, where RagC/D activity and downstream regulation of TFEB/TFE3 seem to be particularly affected, highlighting FLCN-Rag-mTORC1-TFEB as an important signaling axis in human disease." (PMID 35822019, 2021).
bladder cancer (2 papers, 2021 to 2023). "Together, our results indicate that mTORC1 is active in all bladder cancer cell lines analyzed, despite a nuclear localization of TFEB in KU19-19 and JMSU1 cells that correlates with an activation of TFEB-regulated CLEAR network genes." (PMID 36709383, 2023). "Altogether, our findings uncover peripheral lysosome positioning, resulting from PtdIns3P production downstream of TFEB activation, as a potential biomarker for bladder cancer." (PMID 36709383, 2023). "Altogether, our results indicate that endosomal PtdIns3P levels dictate lysosomal positioning and are regulated by TFEB in bladder cancer cells." (PMID 36709383, 2023). "In aggressive bladder cancer cells, the transcription factor EB is activated, leading to increased endosomal phosphatidylinositol-3-phosphate levels and lysosome dispersion to the cells’ periphery." (PMID 36709383, 2023). "Notable, nuclear TFEB appeared to have a higher molecular weight than cytosolic TFEB in bladder cancer cell lines." (PMID 36709383, 2023). "In conclusion, we discovered unexpected phenotypes in terms of TFEB dynamics in aggressive bladder cancer cells lines." (PMID 36709383, 2023). "We identify transcription factor EB (TFEB) as an upstream regulator of PtdIns3P production by VPS34 that is activated in aggressive bladder cancer cells with peripheral lysosomes." (PMID 36709383, 2023). "Together our results propose that the lysosome phenotype in bladder cancer cells is controlled by endosomal PtdIns3P production by VPS34 that are partly under transcriptional regulation by TFEB." (PMID 36709383, 2023). "Thus, several parallel mechanisms seem to regulate PtdIns3P production in bladder cancer cell lines that result in TFEB-dependent and independent lysosome movements." (PMID 36709383, 2023). "To further test whether this nuclear localization indicated hyperactivation of TFEB in cell lines representing high-grade cancers we performed a GSEA (Gene Set Enrichment Analysis) of the transcriptome of bladder cancer cell lines." (PMID 36709383, 2023).
chromophobe renal cell carcinoma (2 papers, 2022 to 2024). Chromophobe renal cell carcinoma is a rare subtype of renal cell carcinoma, originating from the intercalating cells of the collecting ducts and macroscopically manifesting as a well-circumscribed, highly lobulated, solid tumor that is usually diagnosed at an early stage. "CK7, S100A1, and parvalbumin are helpful immunohistochemical markers in the differential diagnosis between chromophobe renal cell carcinoma and TFE3/TFEB-rearranged renal cell carcinoma." (PMID 35980471, 2022).
chronic pancreatitis (2 papers, 2020 to 2024). A chronic inflammatory process causing damage and fibrosis of the pancreatic parenchyma. "However, deletion of TFEB in acinar cells markedly exacerbates pancreatic degeneration, inflammation, and fibrosis, which mimic the features of chronic pancreatitis, after the mice were fed with Lieber-DeCarli liquid diet regardless of ethanol feeding." (PMID 31987928, 2020). "Perhaps the most intriguing findings in this study are the acinar cell–specific Atg5 or TFEB KO mice developed severe pancreatic changes reminiscent of chronic pancreatitis in the Lieber-DeCarli control diet–fed mice regardless of alcohol feeding." (PMID 31987928, 2020).